IL6 (interleukin 6)
Diseases named in the same sentence as IL6 in open-access papers (continued):
Sharing a sentence is not in itself a finding about the gene and the disease.
cancer (continued). "In this regard, it has been shown that solid tumor cells may secrete high levels of IL-6, which is involved in fundamental processes in cancer metastasis, i.e., angiogenesis, proliferation, attachment, and invasion." (PMID 36766760, 2023). "It regulates the transcriptional activity of hypoxanthine catabolic enzyme xanthine dehydrogenase (XDH) in cancer cells presumably by regulating the mRNA level of XDH transcriptional stimulators IL-6, TNF-α, and IFN-γ, and promotes the catabolism of hypoxanthine." (PMID 37658353, 2023). "NK-LAAO treatment using a non-toxic condition (0.1 μg/ml for 18 h) led to approximately 1.3- and 1.2-fold increases in the migratory and invasive abilities, respectively, of cancer cells while these effects could be counteracted by IL-6 depletion." (PMID 37385076, 2023). "The flavonoid dihydroquercetin, extracted from onions, promotes anti-cancer and anti-inflammatory effects via the induction of apoptosis in cancer cells and the inhibition of pro-inflammatory agents, including NF-kB, TNFα, IL-1β, and IL-6, in LPS-treated cancer and immune cells." (PMID 38140352, 2023). "Human cross-sectional studies support that regular moderate physical exercise releases anti-inflammatory cytokines and reduces the production of pro-inflammatory cytokines or cancer biomarkers, such as tumor necrosis factor-alpha (TNFα), interleukin-6 (IL-6), and C-reactive protein (CRP)." (PMID 36765772, 2023). "In addition, TAM infiltration significantly correlates with counts of IL-6+ cancer cells; IL-6 is one of the major pro-inflammatory cytokines in the TME." (PMID 36928373, 2023). "Dietary vitamin K (phylloquinone) consumption has been known to have an inhibitory effect on systematic inflammation by reducing the level of proinflammatory cytokines, including tumor necrosis factor-α and interleukin-6,41 a well-known factor for driving the initiation and development of cancer." (PMID 35871570, 2023). "In addition, the deficiency of CX3CR1 expression in macrophages altered the cytokine secretion with a decrease in interleukin 6, a crucial mediator of cancer cell survival and proliferation." (PMID 38001732, 2023). "The results showed that RS was closely related to KRAS signaling up, EMT and other pathways related to cancer development and metastasis, and the immune-related pathways IL6 JAK STAT3 signaling and IL2 STAT5 signaling were significantly different in patients with high and low RS." (PMID 37773804, 2023). "Interestingly, we found that the cancer cells (Cancer cells 2) that propagated after DTX treatment also expressed Il6 gene." (PMID 37699010, 2023). "In addition to a direct autocrine effect on cancer cells themselves, IL-6 acts in a paracrine manner to skew macrophage polarization into an M2-like phenotype." (PMID 37696858, 2023). "In consideration of IL-6 as the major cytokine participant in STAT3 activation and its significance in cancer formation and suppressing the antitumor immune response, we further examined the effect of 11c on IL-6-induced STAT3 activation cell lines such as Hela and MB231 cells." (PMID 37103357, 2023). "Of these, IL-6 is known to be a cytokine that leads to chronic inflammation in several cancers." (PMID 37501379, 2023). "Namely, OS could lead to chronic inflammation, which could then mediate cancer development and extensive research has demonstrated an association with interleukin-6, C-reactive protein (CRP), and ferritin, with cancer." (PMID 37965473, 2023). "Additionally, we showed that TNFAIP8, the IL-6 cytokine receptor, and IL-6-activated STAT3 pathway activity increased following FFAR2 reduction in the all cancer group." (PMID 37296861, 2023).
cancer (continued). "Moreover, our data revealed that serum CRP concentration correlated with the presence of lymph node and distant metastases, advanced cancer stage and gastric wall invasion, while IL-6, CEA and CA 19-9 levels correlated with nodal involvement." (PMID 37240178, 2023). "This is in line with the chief role of IL-6 in driving disease states during cancer development." (PMID 37893079, 2023). "Altogether, IL-6 confers cancer cells a robust tolerance to oxidative stress induced by NK-LAAO." (PMID 37385076, 2023). "In the Th1 environment, pro-inflammatory cytokines IL-1α, IL-1β, and IL-6 may participate in cancer eradication by recruiting white blood cells from the circulation and stimulating cells." (PMID 37893233, 2023). "Furthermore, Fc-VFD inhibits the secretion of proangiogenic factors, VEGF-A and IL-6, from cancer cells in the TME and inhibits angiogenesis and tumorigenesis." (PMID 35895109, 2023). "The current results indicate an increased expression of both interleukins in HepG2 cells, which are cancer cells that may already have altered IL-6 and IL-10 expression themselves." (PMID 37107193, 2023). "IL-21 is known to be cytokines stimulating the activation of NK cell however, the level of IL-6 in NK-cancer microenvironment may decide the fate of NK cells on hypoxic-induced HCC." (PMID 37501379, 2023). "High IL-6 was often noted in previous cancer cachexia studies in comparison with IL-8." (PMID 36831513, 2023). "Furthermore, chronic gastric inflammation is an important factor in promoting GIM and cancer progression, and IL-6, TNF-α, and IL-1β are characteristic cytokines involved in the inflammatory response." (PMID 38096029, 2023). "Moreover, it was demonstrated that cytokines like IL-6 contribute to adipose wasting in patients with cancer through STAT3-dependent transcriptional changes that increase adipocyte lipolysis." (PMID 37481560, 2023). "Moreover, IL-6 and IL-8 are highly expressed on the cell membrane or in the cytoplasm of malignant tumor cells." (PMID 36693957, 2023). "Studies have shown that radiofrequency electrodes can coagulate and necrosis cancer cells through high temperature and can stimulate the body to produce cytokines such as tumor necrosis factor-α (TNF-α), interleukin-1 (IL-1), and interleukin-6 (IL-6) to inhibit the growth of cancer cells." (PMID 37817253, 2023). "Indeed, the IL-6 gene is recognized as a pro-inflammatory cytokine and has a significant function in the pathogenesis of numerous cancer types." (PMID 38024543, 2023). "IL-6 is involved in various processes, including inflammation, autoimmune reactions, metabolism and cancer, and its levels increase during aging and in the presence of cancer." (PMID 37895144, 2023). "Although the underlying cause of low albumin levels in cancer patients remains unknown, it has been demonstrated that high levels of IL-6 produced by cancer cells inhibit the production of albumin." (PMID 37509622, 2023). "Based on the difference in efficacy and the levels of IFN-β and IL-6, the potent anti-cancer effect of Nexavant may need to be further investigated." (PMID 38136298, 2023). "The conditioned medium collected from HSPB1-overexpressing cells significantly promoted the migration of cancer cells and macrophages as well as the angiogenesis of HUVECs, which could be abrogated by the supplement of IL6 neutralizing antibodies." (PMID 37454220, 2023). "Furthermore, CAFs elicit TGF-β-mediated EMT in ovarian cancer cells via IL-6-regulated JAK2/STAT3 pathway to inhibit cancer cell apoptosis and provide paclitaxel resistance." (PMID 37065872, 2023). "In addition, cancer-stimulated production of inflammatory cytokines (e.g., tumor necrosis factor-α, IL-1, IL-6, and interferon-γ) inhibits erythropoiesis and leads to Hb decline." (PMID 36661734, 2023). "One potential explanation for this finding is that in female mice, IL‐6 generation is obstructed by estrogen steroid hormones, which could protect against cancer progression." (PMID 37326149, 2023).
cancer (continued). "Additionally, IL-6 neutralizing antibodies also reversed the expression profile of cancer stem cells and EMT markers induced by CM from TaglnOE iMEFs." (PMID 36990991, 2023). "Moreover, activation of the IL-6/JAK1 axis enhanced PD-L1 phosphorylation by Janus kinase 1 to promote cancer immune evasion." (PMID 36980527, 2023). "Interleukin (IL)-6 is a cytokine with a broad range of effects on immune and cancer cells." (PMID 37173424, 2023). "As proposed by some researchers, the correlation between PMR and cancer could be an altered immune response, and an increased release of some cytokines, such as interleukin-6 (IL-6), is common in both conditions." (PMID 37374068, 2023). "This reduction may contribute to the promotion of TNFAIP8 and IL-6/STAT3, ultimately provoking inflammation and potentially increasing the risk of developing cancer." (PMID 37296861, 2023). "The results demonstrated that IL-1β and IL-6 in Omicron-infected cancer patients were lower than those in non-Omicron-infected cancer patients (P <0.05) and higher than those in Omicron-infected non-cancer-afflicted subjects (P <0.01), respectively." (PMID 37035158, 2023). "Serum IL-6 concentration is elevated in several types of cancer." (PMID 36832045, 2023). "Double strand breaks in cancer cells occur spontaneously, a phenomenon termed ‘self-inflicted DNA DSBs’ which sustain tumorigenesis and maintain the expression/secretion of main inflammatory factors (IL6, IL8, GROα, ICAM-1, Cox-2)." (PMID 36982207, 2023). "IL-6 was reported to be a multifunctional α-helical cytokine that mediates cell growth and differentiation in various tissues and plays important roles in immune response, acute phase reactions, hematopoiesis, bone metabolism, and cancer progression." (PMID 37560319, 2023). "Therefore, a deeper understanding of the IL-6/STAT3 signaling pathway is needed to promote the overall survival of patients with cancer." (PMID 36720310, 2023). "The overproduction of these two cytokines has been indicated in many other cancer types, indicating that increasing miR-155 expression by interfering with IL-6 and IL-10 could be an alternative approach for other type of cancer." (PMID 37928272, 2023). "It has been shown that IL‐6, secreted from cancer cells, directly affects muscle metabolism, which is in line with our finding that CHX207‐conditioned medium caused a reduction in myotube diameter and indicates that fat and muscle catabolism are not causally linked in the CHX207 model of CAC." (PMID 36351437, 2023). "The resulting PGE2 cooperating with IL-1 paracrine signaling further promotes BM-MSCs to release IL-6, IL-8 and GRO-α, causing the accumulation of β-catenin in cancer cells and the formation of ALDHhigh CSCs associated with increased capacity for cancer cell metastasis and invasion." (PMID 37124519, 2023). "IL-6 is a cytokine produced by cancer cells, CAFs, immune cells, and adipose cells in the TME." (PMID 36635302, 2023). "In addition to the IL-6 derived from CAFs, IL-6 can be secreted from BCA cells which then promotes cancer cell metastasis in an autocrine effect." (PMID 37480115, 2023). "In addition, IL-6 is important in regulating cancer stem cell self-renewal and the balance between cancer cells and cancer stem cells in several types of cancer." (PMID 38136303, 2023). "Interestingly, both IL-6 and another cytokine that signals through a gp130 receptor, OSM, have been associated with cancer cachexia, due to catabolic effects these cytokines have on muscle protein." (PMID 38022653, 2023). "Additionally, we previously reported that cancer stimulus activated normal fibroblasts into CAFs and also triggered IL-6 secretion from CAFs." (PMID 36764954, 2023).
cancer (continued). "STAT3 was identified as the major mediator of IL-6-dependent cancer cell proliferation in RCCs." (PMID 37190141, 2023). "Similarly, IL-6 produced mainly by macrophages and cancer cells, plays a critical role in promoting angiogenesis, ascites development, and T-cell exhaustion." (PMID 38164130, 2023). "More importantly, studies focusing on reversing the adverse influence of endogenous GC on immunity and immunotherapy, such as controlling cancer-related depress and chronic stress with agents, combined IL-6 blockade, and interrupting the GR signaling with targeted molecules, are urgently expected." (PMID 37114049, 2023). "We found that the positive feedback loop of PDGFB signaling and IL6 signaling between cancer cells and CAFs could substantially benefit the immune-suppressive stroma." (PMID 37658364, 2023). "In addition, NF-κB/IL-6/STAT3 axis plays a key role in cancer chemotherapeutic resistance, where NF-κB can activate IL-6, which then can subsequently activate STAT3 through its receptor." (PMID 37818040, 2023). "IL-6 inhibits the effector differentiation of CD8+ T cells (also known as cytotoxic T lymphocytes or CTLs), and high plasma IL-6 is associated with lower expression of effector genes in CTLs of cancer patients." (PMID 37240834, 2023). "Additionally, an unbiased mass spectrometry-based secretome analysis conducted in lung cancer cells has revealed that ERK5 is crucial for IL-6 production in cancer cells, and inhibiting or depleting ERK5 prevented this observed phenotype." (PMID 37601096, 2023). "Our data confirmed the hypothesis related to IL-6 as a therapeutic target in cancer marked by STAT3 expression and cisplatin resistance." (PMID 36979673, 2023). "Recognition of these cognate cancer‐specific antigens by the engineered antibodies causes to initiation of some signaling pathways in T cells that induce production of several pro‐inflammatory cytokines (IFN‐γ, TNF‐α, IL‐6, and IL‐2) and cytolysis (osmotic lysis) of cancer cells." (PMID 36583504, 2023). "Besides, STAT3 plays an important role in maintaining and promoting the tumorigenic inflammatory environment, the transformation and progression of malignant tumours based on NF‐κB and IL‐6/GP130/JAK pathways." (PMID 35961680, 2023). "IL-6 is a pro-inflammatory cytokine that is synthesized primarily by the B and T lymphocytes and also by macrophages and monocytes, with an important role in adaptive immunity and a proven role in chronic inflammation and different types of cancer." (PMID 38137862, 2023). "We expected that the treatment of rhIL-21 in the co-culture of HIF-1α-expressed HCC SK-Hep1 cells and NK-92 cells could enhance the effector function of NK cells against cancer cells compared to the treatment of IL-6 antibody alone." (PMID 37501379, 2023). "To investigate the relationship between CAFs in the TME and serum IL-6, we analyzed three groups with varying amounts of fibroblasts: cancer cells alone (Colon26), co-inoculated cancer cells and fibroblasts (Colon26 + 1NIH/3T3, 1:1), and co-inoculated cells with Colon26 + 2NIH/3T3 (1:2)." (PMID 36764954, 2023). "Indeed, we observed a significant increase in IL-6 postoperatively, consistent between all cancer types and reaching peak levels on POD1 before normalizing to baseline." (PMID 38067195, 2023). "A high level of IL-6 in the interaction of highly invasive HCC-NK cells could diminish the NK cancer-surveillance." (PMID 37501379, 2023). "In addition, ORC6 was negatively correlated with several immune pathways (e.g., IL2-STAT5 signaling, inflammatory response and IL6-JAK-STAT3 signaling) in the majority of cancers." (PMID 36978046, 2023). "Therefore, based on clinical and experimental evidence, drugs targeting the IL-6 signal are reasonable partners for cancer patients and ICIs in combination treatment." (PMID 37240834, 2023).
cancer (continued). "Clinical studies also reported reduced inflammation and amelioration of body weight loss by IL‐6 signalling pathway inhibition, indicating that targeting IL‐6 signalling may be a promising adjunct strategy for cancer treatment." (PMID 36351437, 2023). "This could help to unveil how interleukin 6 and other myokines are released in pathological conditions such as trauma, infections or cancer." (PMID 37508398, 2023). "Furthermore, the concentration of IL-6, an inflammatory cytokine, in each CM was significantly higher in CM-RF than in CM-NF, suggesting acquisition of cancer cell malignancy through secretion of IL-6 in CM-RF." (PMID 37296933, 2023). "These included production of Interleukin 6, cytokine secretion, and T-cell activation, all of which could lead to immune-induced cytotoxic activity that could destroy cancer cells, or chronic inflammation and escape in favor of cancer progression." (PMID 37612266, 2023). "As the stromal compartment was highly viable during treatments, synergistic effects between cancer and stromal cells may result in robust IL‐6 secretion in multicellular 3D cultures, which declined in response to immunomodulatory treatment." (PMID 36417691, 2023). "Furthermore, macrophages co-cultured with SA/Dox-treated IL-6-silenced A549 cells exhibited decreased pro-migratory and -invasive effects on cancer cells compared to those co-cultured with SA/Dox-treated control cells." (PMID 37696858, 2023). "Cancer survivors had plasmatic IL-6 levels comparable to healthy controls." (PMID 37108527, 2023). "In a study that involved the clustering of cancer symptoms and cytokine levels, female patients were over-represented in groups with moderate/high fatigue; those groups also had significantly higher levels of proinflammatory cytokine IL-6." (PMID 37835558, 2023). "•NK-LAAO treatment enables cancer cells to produce IL-6 via the Panx1/iCa2+ pathway." (PMID 37385076, 2023). "IL-6 plays a critical role in inflammation and cancer development." (PMID 37853413, 2023). "In consequence, we hypothesize that the rs181747 CC genotype affects the binding of PRRX2 to IL-6 and that the generated IL-6 contributes to cancer development and progression via p-STAT3 and facilitates chemotactic movement of immune cells." (PMID 37035153, 2023). "For example, cancer cells secrete IL-6 and TGF-β, which may encourage the expression of genes through autocrine or paracrine signaling." (PMID 37174117, 2023). "Moreover, IL-6 plays a central role in promoting inflammation and cancer promotion in OC, making it an attractive therapeutic target." (PMID 37818040, 2023). "Neutralisation of IL-6/G-CSF was able to prevent docetaxel-induced activation of dormant cancer cells in vivo; however, it remains to be determined if IL-6/G-CSF inhibition can revert awakened cancer cells to a dormant state." (PMID 37703292, 2023). "Using models for cancer stem cell features and patient-based cancer microenvironments, we could validate the effect of IL-6 and progranulin in promoting cancer stem cells via the sortilin receptor." (PMID 38136303, 2023). "Although the CRS is likely of higher grade in cancer patients with severe SARS-CoV-2 due to greater IL-6 production, the use of combination therapies offers a promising solution to mitigate the local and systemic nature of SARS-CoV-2 and its resulting cytokine production." (PMID 37055774, 2023). "Studies have shown that when malignant tumors progress, the function of T lymphocytes is damaged, the expression of IL‐6 can be enhanced, aggravating the inflammatory response, leading to the weakening of immune regulation function and the decline of immune level." (PMID 37904699, 2023). "Pro-inflammatory cytokine IL-6 play a central role in chronic inflammatory including cancers." (PMID 37215450, 2023).